LCN2 (lipocalin 2)
Diseases named in the same sentence as LCN2 in open-access papers (continued):
Sharing a sentence is not in itself a finding about the gene and the disease.
mycoplasma infection (3 papers, 2020 to 2021). "In other infections, such as mycoplasma infection, the expression of LCN2 in HC11 cells needs to be regulated by NF-κB." (PMID 34616693, 2021). "Here we show that Lcn2 gene expression is increased by mycoplasma infection and by MALP-2, the mycoplasma lipopeptide." (PMID 32376831, 2020). "A comparison of the activities of a range of truncated mouse Lcn2 promoters showed that the shortest length of promoter to respond to mycoplasma infection was a 253 bp fragment containing the NFκB and C/EBP response elements." (PMID 32376831, 2020). "Here we extend the microbial activators of Lcn2 to mycoplasma and describe studies in which the mechanism of Lcn2 gene regulation by MALP-2 and mycoplasma infection was investigated in mouse mammary epithelial cells." (PMID 32376831, 2020).
myeloproliferative neoplasm (3 papers, 2020 to 2025). A clonal hematopoietic stem cell disorder, characterized by proliferation in the bone marrow of one or more of the myeloid (i.e., granulocytic, erythroid, megakaryocytic, and mast cell) lineages. "Lipocalin 2 (LCN2) is a proinflammatory mediator increased in the blood of patients with myeloproliferative neoplasms (MPN) and other hematologic malignancies, significantly contributing to MPN disease initiation and progression." (PMID 34439364, 2021). "In addition, LCN2-mediated tumourigenesis has been reported in human cutaneous squamous cell carcinoma xenograft models and myeloproliferative tumour cell lines." (PMID 40109857, 2025). "Lipocalin 2 (LCN2), a proinflammatory mediator, is involved in the pathogenesis of myeloproliferative neoplasms (MPN)." (PMID 34439364, 2021).
myocarditis (3 papers, 2022 to 2024). Myocarditis is a condition that is characterized by inflammation of the heart muscle (myocardium). "Finally, we investigated the role of Lcn2 in viral-induced myocarditis." (PMID 38750107, 2024).
neutropenia (3 papers, 2015 to 2022). A decrease in the number of neutrophils found in the blood. "Moreover, because LCN2 is expressed in complex with MMP9 in neutrophils specifically, we asked whether the decline in serum levels might have reflected grave neutropenia during NACT and CRT." (PMID 27461255, 2016).
optic neuritis (3 papers, 2021 to 2023). Optic neuritis is inflammation of the optic nerve, the nerve that carries the visual signal from the eye to the brain.The conditionmay cause sudden, reduced vision in the affected eye(s). "Nevertheless, limited data are available regarding the association of plasma LCN2 levels with optic neuritis." (PMID 35566760, 2022). "The LCN2 and MOG-IgG correlation supports the immune and inflammatory nature of MOG-IgG positive optic neuritis, as LCN2 has been strongly associated with neuroinflammation." (PMID 35566760, 2022). "We plan to investigate the molecular mechanism underlying the increased plasma LCN2 levels in patients with MOG-IgG–positive optic neuritis with a focus on clinical factors that may influence plasma LCN2 levels in patients with MOG-IgG associated disorders." (PMID 35566760, 2022). "Therefore, our results indicate that plasma LCN2 levels can be used in clinical practice as a prompt diagnostic marker for MOG-IgG–positive optic neuritis." (PMID 35566760, 2022). "Therefore, our results highlight the diagnostic value of plasma LCN2 levels for differentiating MOG-IgG–positive optic neuritis from MOG-IgG–negative optic neuritis." (PMID 35566760, 2022). "The plasma LCN2 levels were positively correlated with MOG-IgG titers in patients with optic neuritis (r = 0.553, p = 0.0141); i.e., patients with higher plasma LCN2 levels demonstrated higher titer of MOG-IgG." (PMID 35566760, 2022). "Plasma LCN2 levels were positively correlated with MOG-IgG titers in patients with optic neuritis (r = 0.553, p = 0.0141); that is, patients with high plasma LCN2 levels demonstrated high MOG-IgG titers." (PMID 35566760, 2022). "We also demonstrated that patients with optic neuritis had significantly higher plasma LCN2 levels than healthy controls." (PMID 35566760, 2022). "Patients with MOG-IgG–positive optic neuritis had significantly higher mean plasma LCN2 levels than controls and patients with MOG-IgG–negative optic neuritis (50.96, 30.86, and 37.60 ng/mL, respectively, p = 0.037)." (PMID 35566760, 2022). "The mean plasma LCN2 values were significantly higher in the patients with MOG-IgG positive optic neuritis when compared to controls and patients with MOG-IgG negative optic neuritis." (PMID 35566760, 2022). "Lcn2 is localized to optic nerve astrocytes in optic neuritis, but it’s localization in the glaucomatous optic nerve is unknown." (PMID 37759301, 2023). "Additionally, plasma LCN2 levels were positively correlated with MOG-IgG titers in patients with optic neuritis." (PMID 35566760, 2022). "Plasma LCN2 levels may aid differentiation of MOG-IgG–positive optic neuritis from MOG-IgG–negative optic neuritis." (PMID 35566760, 2022). "Our results imply that measurement of plasma LCN2 levels may be helpful in differentiating MOG-IgG–positive optic neuritis from MOG-IgG–negative optic neuritis." (PMID 35566760, 2022). "Therefore, we hypothesized that measuring the plasma LCN2 levels in patients with optic neuritis may help in the diagnosis of MOG-IgG–positive optic neuritis." (PMID 35566760, 2022). "Quantification of plasma LCN2 levels by ELISA in healthy controls (n = 20), patients with MOG-IgG negative optic neuritis (n = 13), and patients with MOG-IgG positive optic neuritis (n = 6)." (PMID 35566760, 2022). "This study aimed to evaluate the correlation between plasma lipocalin-2 (LCN2) levels and myelin oligodendrocyte glycoprotein (MOG)-immunoglobulin G (IgG) seropositivity in patients with optic neuritis." (PMID 35566760, 2022). "Receiver operating characteristic (ROC) curves were constructed to assess and compare the ability of plasma LCN2 and MOG-IgG levels for predicting optic neuritis recurrence." (PMID 35566760, 2022). "The correlation between plasma LCN2 levels and MOG-IgG titers in patients with optic neuritis was analyzed." (PMID 35566760, 2022).
optic neuritis (continued). "We found that patients with MOG-IgG–positive optic neuritis had significantly higher plasma LCN2 levels than healthy controls and patients with MOG-IgG–negative optic neuritis." (PMID 35566760, 2022). "In this study, we investigated the correlation between plasma LCN2 levels and MOG-IgG titers in patients with optic neuritis." (PMID 35566760, 2022). "Plasma LCN2 levels were significantly higher in patients with MOG-IgG–positive optic neuritis than in controls and patients with MOG-IgG–negative optic neuritis." (PMID 35566760, 2022). "Patients with MOG-IgG–positive optic neuritis had significantly higher mean plasma LCN2 levels than controls and patients with MOG-IgG–negative optic neuritis (p = 0.037)." (PMID 35566760, 2022). "The purpose of this study was to measure plasma LCN2 levels and evaluate their correlation with MOG-IgG titers in patients with optic neuritis." (PMID 35566760, 2022). "We believe this is the first study that evaluated the plasma LCN2 levels and their correlation with MOG-IgG titers in patients with optic neuritis." (PMID 35566760, 2022). "Plasma LCN2 and MOG-IgG levels were significantly correlated in patients with optic neuritis (r = 0.553, p = 0.0141)." (PMID 35566760, 2022). "Our results demonstrated that plasma LCN2 levels were significantly higher in patients with MOG-IgG–positive optic neuritis than in controls and patients with MOG-IgG–negative optic neuritis, and plasma LCN2 levels were positively correlated with MOG-IgG titers." (PMID 35566760, 2022).
peripheral vascular disease (3 papers, 2017 to 2023). Any disorder affecting blood flow through the veins or arteries outside of the heart. "We found that APOE, IGF1R, HMGCR, APOA1, ENG, SERPINA3 and LCN2 were hub proteins in the network, which were also predicted to be associated with peripheral vascular disease." (PMID 37496672, 2023).
pneumococcal infection (3 papers, 2014 to 2021). Infections with bacteria of the species streptococcus pneumoniae. "In contrast, in a pneumococcal infection model, Lcn2 expression by neutrophils resulted in decreased survival of mice." (PMID 29329289, 2018).
pustular psoriasis (3 papers, 2019 to 2024). "In addition, as seen with the marked improvement in our model with both TLR4 inhibition, and LCN2 blockade, these provide additional novel therapeutic targets in both chronic plaque and pustular psoriasis." (PMID 31024570, 2019). "Also, the authors have highlighted a positive correlation between the level of lipocalin-2 and disease severity using different scales (PASI, body surface area), including those used for nail or pustular psoriasis (nail psoriasis severity index, and pustular severity index)." (PMID 38399624, 2024).
retinitis pigmentosa (3 papers, 2020). Retinitis pigmentosa (RP) is an inherited retinal dystrophy leading to progressive loss of the photoreceptors and retinal pigment epithelium and resulting in blindness usually after several decades. "Furthermore, increased plasma levels of LCN2 have been observed in patients with Stargardt disease, retinitis pigmentosa, and AMD." (PMID 33292361, 2020).
Splenomegaly (3 papers, 2018 to 2023). Abnormal increased size of the spleen. "Other indices of inflammation were more variable in that P80 also induced elevations in faecal Lcn2 and colon weight/length ratio, while CMC induced mild splenomegaly." (PMID 36646449, 2023).
Ureteral obstruction (3 papers, 2016 to 2024). Obstruction of the flow of urine through the ureter. "In the present study, we characterized two subpopulations of LCN2 with distinct molecular weights, 22- and 24-kDa LCN2, in the urine from model mice with LPS-induced inflammation or ureteral obstruction." (PMID 26949374, 2016). "Interestingly, ureteral obstruction predominantly induced the 24-kDa LCN2 isoform in bladder urine, which was derived from the unobstructed side of kidney and ureter." (PMID 26949374, 2016). "The distribution patterns of urinary 22- and 24-kDa LCN2 varied between the LPS-treated and ureteral obstruction model mice, suggesting that the emergence of the two different glycosylated urinary LCN2 isoforms could differ according to the pathological conditions." (PMID 26949374, 2016). "Moreover, the 24-kDa form of LCN2 could be detected in urine from mice with experimental unilateral ureteral obstruction." (PMID 26949374, 2016).
uveitis (3 papers, 2010 to 2025). An inflammatory process affecting a part of or the entire uvea. "In acute inflammatory settings such as endotoxin-induced uveitis, LCN2 demonstrated protective anti-inflammatory properties by suppressing NF-κB p65 phosphorylation and nuclear translocation in Müller cells and retinal tissues." (PMID 40375133, 2025). "Among those genes, a few are already known to be implicated in uveitis, such as E and P selectins, CD44, IL-33 and Lcn2." (PMID 32183784, 2020). "In the field of uveitis, lcn2 was reported to be highly induced in the equine recurrent uveitis model." (PMID 32183784, 2020).
Acute hepatitis (2 papers, 2023 to 2024). Acute hepatic injury resulting from inflammation typically accompanied by increased serum alanine transaminase activity. "IκBζ-dependent genes include IL-6 and lipocalin-2 that contribute to controlling acute hepatitis and bacterial infection." (PMID 36978599, 2023).
age (2 papers, 2022 to 2024). A temporal measurement of the time period elapsed since an identifiable point in the life cycle of an organism. "Therefore, elevated Lcn-2 levels can be considered a risk factor for age-related CNS disorders." (PMID 35912090, 2022). "Consistent with this, both systemic and central nervous system expression of LCN2 are increased in age-related central nervous system disorders, along with an increase in LCN2 with age." (PMID 38673873, 2024).
alopecia areata (2 papers, 2022 to 2024). Loss of scalp and body hair involving microscopically inflammatory patchy areas. "The aim of the study is to determine the serum levels of lipocalin-2 and visfatin in patients with alopecia areata in comparison with healthy controls." (PMID 35639706, 2022). "In the present study, an increased serum level of lipocalin-2 was observed in patients with alopecia areata compared to healthy controls (p = 0.01)." (PMID 35639706, 2022). "A higher serum concentration of lipocalin-2 was observed in patients with alopecia areata than in the controls (p = 0.01)." (PMID 35639706, 2022). "To date, data considering the role of lipocalin-2 and visfatin in alopecia areata is limited." (PMID 35639706, 2022). "The results of the present study suggest that lipocalin-2 and insulin may serve as biomarkers in alopecia areata." (PMID 35639706, 2022). "In conclusion, lipocalin-2 and insulin may serve as biomarkers for alopecia areata." (PMID 35639706, 2022). "To date, lipocalin-2 has not been evaluated in alopecia areata." (PMID 35639706, 2022).
amebiasis (2 papers, 2022). A parasitic infectious disorder caused by amoebas. "For example, among amoebiasis pathway-related proteins, integrin beta-2 (ITGB2), heat shock protein beta-1 (HSPB1), LCN2, leukocyte elastase inhibitor (SERPINB1), laminin subunit alpha-4 (LAMA4), and fibronectin (FN1) have been found to be correlated with immunity." (PMID 36387401, 2022).
amyloid (2 papers, 2016 to 2022). "On the other hand, LCN2 deficiency in an AD mouse model led to decreased iron accumulation in the hippocampus but not to altered symptoms, amyloid plaque load, or glial activation." (PMID 35027079, 2022). "To finally explore the potential relationship between PBA and LCN2 in humans, we took advantage of a patient followed in our nephrology department for a lysinuric protein intolerance (a urea cycle disorder due to a SLC7A7 gene mutation), which was associated with amyloidosis and proteinuria." (PMID 26787103, 2016).
anorexia nervosa (2 papers, 2023 to 2024). A disorder most often seen in adolescent females characterized by a refusal to maintain a minimally normal body weight, an intense fear of gaining weight, a disturbance in body image, and, in postmenarcheal females, the development of amenorrhea. "We aimed to (i) detect variants in the lipocalin-2 gene (LCN2) which are relevant for body weight regulation and/or anorexia nervosa (AN); (ii) describe and characterize the impact of LCN2 and MC4R variants on circulating lipocalin-2 level." (PMID 37025415, 2023).
Arrhythmia (2 papers, 2022 to 2024). Any cardiac rhythm other than the normal sinus rhythm. "Further research is warranted to elucidate exact pathomechanisms and the Lcn2-arrhythmia axis in MI and other rhythm disorders." (PMID 38099844, 2024). "We found that, similarly to neutrophil depletion, deleting Lcn2 from bone-marrow-derived leukocytes reduced the arrhythmia burden." (PMID 36034743, 2022). "Using quantitative RT–PCR in sorted immune cells, we verified that neutrophils express Lcn2 at high levels when post-MI arrhythmias peak." (PMID 36034743, 2022).
Atrophy (2 papers, 2023). Any weakening or degeneration, especially through lack of use. "In the atrophy model, however, Lcn2 expression was persistently high in the first 14 days after IRI." (PMID 36951957, 2023). "The persistently high expression of injury marker Lcn2 in the early course (days 1–14) after IRI in the atrophy model is likely due to the accumulation of Lcn2-expressing neutrophils." (PMID 36951957, 2023).
autoimmune optic neuritis (2 papers, 2021 to 2022). An autoimmune form of optic neuritis. "Finally, LCN2 has been reported to exert detrimental effects on remyelination and to be involved in demyelination as well as gliosis progression in an experimental autoimmune optic neuritis model (EAON)." (PMID 35380252, 2022).
bronchiectasis (2 papers, 2022 to 2023). Segmental, irreversible dilation of the bronchial tree resulting in the accumulation of secretions which leads to obstruction. "It has a similar incidence to NTHi in stable bronchiectasis, is associated with a systemic inflammatory response and in vitro can induce both cell death and release of proinflammatory cytokines, including CXCL8, TNF and lipocalin 2; such features suggest a pathogenic role." (PMID 36130784, 2022).
chronic lung disease (2 papers, 2023 to 2024). According to the definitions of the American and British Thoracic Societies, including pulmonary functional tests, X-rays, and CT scans for items such as fibrosis, bronchiectasis, bullae, emphysema, nodular or lymphomatous abnormalities. "First, the small sample sizes of patients and controls with stable chronic lung disease may have obscured significance differences of LCN2 in BALF." (PMID 36923935, 2023). "Maybe, we suggest that control subjects in this study consisted of patients with stable chronic lung disease, which may affect LCN2 levels." (PMID 36923935, 2023).
chronic rhinosinusitis (2 papers, 2020 to 2025). Chronic form of sinusitis. "In patients with chronic rhinosinusitis with nasal polyps (CRSwNP), LCN2 is markedly upregulated in association with the IL-17/IL-8 inflammatory axis." (PMID 41369347, 2025). "One such mechanism is mediated by miR-761, which downregulates LCN2/Twist1 expression, thereby attenuating the epithelial–mesenchymal transition (EMT) and matrix reprogramming in chronic rhinosinusitis models." (PMID 41369347, 2025).
colorectal adenoma (2 papers, 2012 to 2016). An adenoma that arises from the colon or rectum. "Recent studies have reported that LCN2 expression is elevated in both the colorectal adenoma-carcinoma sequence and cancer progression." (PMID 27912767, 2016).
eczema (2 papers, 2016 to 2020). "Serum resistin was associated with lipocalin-2 changes when considering the whole AD group (r = 0.37; p = 0.009); the association was notably strengthened in patients with severe eczema (r = 0.60; p = 0.003)." (PMID 32899610, 2020). "In this study, we addressed the contribution of adipokines to AD eczema based on the assessment of blood levels of adiponectin, resistin, leptin, lipocalin-2, and vaspin in adult non-obese patients suffering from chronic extrinsic childhood-onset AD." (PMID 32899610, 2020).
End Stage Liver Disease (2 papers, 2020 to 2024). Final stage of a liver disease when the liver failure is irreversible and LIVER TRANSPLANTATION is needed. "We found that hepatic LCN2 gene expression positively correlated with the main prognostic scores in patients with AH, including the Age/Bilirubin/International normalized ratio/Creatinine (ABIC) score (r = 0.41, p = 0.002) and the Model for End-stage Liver Disease (MELD) score (r = 0.41, p = 0.002)." (PMID 32968110, 2020).
endophthalmitis (2 papers, 2025). An infectious process affecting the internal structures of the eye. "The increased levels of LCN2 in our study indicate its protective role during endophthalmitis." (PMID 40512033, 2025).
gallstones (2 papers, 2016 to 2023). Solid crystalline precipitates in the biliary tract, usually formed in the gallbladder, resulting in the condition of cholelithiasis. "The LCN2 level in patients with CCA was statistically higher than that in gallstone patients (P < 0.001)." (PMID 27782193, 2016). "LCN2 concentration in bile was higher in patients with CCA than that in patients with gallstones, with a cutoff value of 20.08 ng/ml making this a potential diagnostic marker." (PMID 27782193, 2016). "The median LCN2 levels in the bile for 30 patients with CCA and 36 gallstone patients were 59.26 ng/ml and 10.19 ng/ml, respectively." (PMID 27782193, 2016).